ZNF281 (zinc finger protein 281)
Description:
Transcription repressor that plays a role in regulation of embryonic stem cells (ESCs) differentiation. Required for ESCs differentiation and acts by mediating autorepression of NANOG in ESCs: binds to the NANOG promoter and promotes association of NANOG protein to its own promoter and recruits the NuRD complex, which deacetylates histones. Not required for establishement and maintenance of ESCs (By similarity). Represses the transcription of a number of genes including GAST, ODC1 and VIM. Binds to the G-rich box in the enhancer region of these genes.
Synonyms: GZP1; ZBP99; ZBP-99; ZNP-99
Tractability: PROTAC: UniProt records ubiquitination sites on it; ubiquitination databases record sites on it; its protein half-life has been measured.
Gene: Protein-coding gene on chromosome 1 (200,404,940 to 200,410,056, reverse strand). Ensembl gene ENSG00000162702.
Subcellular location: Nucleus
Subcellular location (Human Protein Atlas): Nucleoplasm
Gene Ontology:
Molecular function: DNA-binding transcription factor activity; DNA-binding transcription repressor activity, RNA polymerase II-specific; protein binding; RNA polymerase II cis-regulatory region sequence-specific DNA binding; sequence-specific DNA binding; sequence-specific double-stranded DNA binding; transcription cis-regulatory region binding; DNA-binding transcription factor activity, RNA polymerase II-specific
Biological process: negative regulation of DNA-templated transcription; negative regulation of gene expression; negative regulation of transcription by RNA polymerase II; positive regulation of DNA-templated transcription; embryonic body morphogenesis; regulation of DNA-templated transcription; stem cell differentiation
Cellular component: nucleoplasm; nucleus
Genetic constraint (gnomAD): Loss-of-function variants: 2 observed, 61.04 expected, observed/expected ratio (o/e) 0.0328, 90% interval 0.012 to 0.1. The upper end of that interval is the gene's LOEUF score, 0.1, which puts it in group 1 of 6, group 1 being the genes least tolerant of losing a copy. Missense variants: 975 observed, 1,133.2 expected, observed/expected ratio (o/e) 0.86, 90% interval 0.81 to 0.91. Synonymous variants: 465 observed, 424.75 expected, observed/expected ratio (o/e) 1.09, 90% interval 1.01 to 1.18.
Homologues: Orthologues: rat Zfp281 (95% identical), mouse Zfp281 (95% identical), dog ZNF281 (94% identical), macaque ZNF281 (90% identical), pig ZNF281 (87% identical), rabbit ZNF281 (61% identical), tropical clawed frog znf281 (54% identical), zebrafish znf281b (44% identical), zebrafish znf281a (41% identical). Paralogues in human: ZNF148 (30% identical), MTF1 (14% identical), PATZ1 (13% identical), PRDM10 (11% identical), ZNF76 (11% identical), VEZF1 (10% identical), ZNF143 (10% identical), PRDM1 (9% identical), ZNF451 (9% identical), MAZ (9% identical), ZNF362 (9% identical), ZNF384 (9% identical), and 24 more.
Diseases named in the same sentence as ZNF281 in open-access papers:
ZNF281 is named in the same sentence as 58 diseases in open-access papers, as found by Europe PMC text mining. Sharing a sentence is not in itself a finding about the gene and the disease. The quoted sentences say what the papers report.
colorectal cancer (11 papers, 2017 to 2023). A primary or metastatic malignant neoplasm that affects the colon or rectum. "Compared to control cells, γH2AX levels were reduced more slowly in ZNF281-deficient colorectal cancer cells." (PMID 37939252, 2023). "Furthermore, the upregulation of ZNF281 was shown to be associated with the recurrence of colorectal cancer 3 years after removal of the primary tumor; this implies that overexpression of ZNF281 in primary tumor tissue might have a prognostic value." (PMID 30885238, 2019). "Intriguingly, ZNF281 interference caused p62 deposition and LC3 declination, which triggered autophagy disorder in colorectal cancer cells." (PMID 36514923, 2023). "ZNF281 was reported to be involved in the regulation of autophagy process in UCA1‐mediated 5‐fluorouracil resistance of colorectal cancer cells." (PMID 36514923, 2023). "Zinc finger protein 281 (ZNF281) has been demonstrated to promote metastasis and invasion in lung cancer, pancreatic cancer and colorectal cancer." (PMID 36121916, 2022). "MiR-23b-3p directly binds to the 3′ untranslated region of zinc finger protein 281 (ZNF281) and elevates the 5-FU sensitivity through negatively modulating ZNF281 in colorectal cancer cells." (PMID 36499136, 2022). "Knockdown of lnc-ZNF281 inhibited colorectal cancer cell proliferation, migration, and invasion via the Wnt/β-catenin pathway." (PMID 34056009, 2021). "One study showed that in colorectal cancer, Zinc Finger protein 281 (ZNF281) can be an intermediate regulator between SNAIL1 and miR-34." (PMID 31195692, 2019). "Ectopic expression of ZNF281 was sufficient to induce EMT in colorectal cancer cell lines with epithelial features, and ZNF281was shown to be necessary for SNAIL-induced EMT." (PMID 30885238, 2019). "ZNF281 has been demonstrated to play a crucial role in controlling cellular stemness and EMT by inducing EMT and regulating EMT-associated gene expression in colorectal cancer." (PMID 35164660, 2022). "Besides, lnc-ZNF281 regulates the Wnt/β-catenin pathway to influence the progression of colorectal cancer." (PMID 34056009, 2021). "Given that enhanced expression of ZNF281 in colorectal cancer correlates significantly with clinical stage of the malignancy, this protein might find application in oncological diagnostics, prognosis or even treatment." (PMID 30885238, 2019). "The fact that enhanced expression of ZNF281 in colorectal cancer was shown to correlate significantly with the tumor stage, implies that this protein might be useful in the diagnostics of other human malignancies, establishing prognosis and perhaps also anticancer therapy." (PMID 30885238, 2019). "The fact that the downregulation of ZNF281 prevented formation of lung metastases of a colorectal cancer cell line in a xenograft mouse model, suggests that the ZNF281-mediated enhancement of EMT and/or stemness might be crucial for colorectal cancer progression." (PMID 30885238, 2019).
breast carcinoma (6 papers, 2020 to 2026). "Up-regulation of ZNF-281 gene expression was observed in colon cancer (protein expression), pancreatic cancer (protein and mRNA expression), breast cancer (protein expression), neuroblastoma (protein expression) and ovarian cancer (protein expression)." (PMID 34071380, 2021). "It has also been proven that the DNA repair mechanism is slowed down upon ZNF-281′s silencing due to its role in promoting DNA damage response genes—XRCC2 (in breast cancer) and XRCC4—and stimulating nucleolin and cyclin B1 expression." (PMID 34071380, 2021). "Furthermore, in breast cancer–associated fibroblasts (CAFs), SNHG5 stabilizes ZNF281 mRNA through an m6A-dependent mechanism, upregulating CCL2/CCL5 expression and activating p38 MAPK signaling, which enhances vascular permeability and neovascularization to facilitate PMN formation." (PMID 41550840, 2026). "ZNF281 is a transcriptional repressor involved in EMT that is upregulated in colon and breast cancer and has been suggested to promote these cancers." (PMID 33558504, 2021). "Recently, ZNF281 was shown to activate epithelial to mesenchymal transition (EMT) transcription factors, ZEB1 and SNAI1 via activation of the TGF-β pathway, promoting EMT and metastasis in breast cancer." (PMID 36207293, 2022). "Moreover, miR-34 and SNAIL form a double-negative feedback loop that may feed-forward regulate ZNF281/ZBP99 to promote EMT, which has implications for human colon and breast cancer." (PMID 31947678, 2020).
pancreatic cancer (5 papers, 2021 to 2023). "ZNF281, an oncogene, is associated with poor prognosis in pancreatic cancer, oral squamous cell carcinoma, and neuroblastoma." (PMID 37939252, 2023). "Notably, recent investigations have revealed that ZNF281 is a novel oncoprotein that is frequently overexpressed in human malignancies, including colorectal and pancreatic cancers." (PMID 33320427, 2022). "Moreover, by activating the Wnt/β-catenin pathway, lnc-ZNF281 promoted cell proliferation and invasion in pancreatic cancer cells." (PMID 34056009, 2021). "Additionally, ZNF281 promotes cell growth and invasion in pancreatic cancer." (PMID 36142169, 2022).
colon carcinoma (4 papers, 2017 to 2024). "Moreover, EMT is activated by ZNF281 in colon cancer cells through the regulation of SNAI1 and other EMT-related gene expressions." (PMID 39518154, 2024). "Indeed, ZNF281 induces epithelial–mesenchymal transition (EMT) in colon cancer cells by regulating the expression of SNAIL1 and other key genes implicated in EMT." (PMID 39518154, 2024). "Interestingly, ZNF281 silencing in lung cancer cell A549 and colon cancer cell line HCT-8 also significantly increased mitotracker green staining, indicating that inhibition of ZNF281 on mitochondrial biogenesis was not limited to HCC." (PMID 37880213, 2023).
glioma (4 papers, 2021 to 2024). A benign or malignant brain and spinal cord tumor that arises from glial cells (astrocytes, oligodendrocytes, ependymal cells). "The purpose of this study is to elucidate the roles and potential underlying mechanisms of long noncoding RNA lnc-ZNF281 in glioma." (PMID 34056009, 2021). "The results showed that the expression of lnc-ZNF281 in glioma tissues was decreased compared with normal tissues." (PMID 34056009, 2021). "We found that down-regulation of ZNF-281 gene expression also exists in glioma and non-small cell lung cancer (NSCLC)." (PMID 34071380, 2021). "More clinical tissues should be used to confirm the expression levels of lnc-ZNF281 in glioma tissues and cell lines." (PMID 34056009, 2021). "In glioma, it is confirmed that ZNF-281 reduces glioma stem-like cells’ invasive ability via down-regulation of NF-κB1 and MMP9 protein expression in vitro and in vivo." (PMID 34071380, 2021). "Here, we found that lnc-ZNF281 suppressed glioma cell proliferation and migration and downregulated AKT/GSK-3β/β-catenin signaling pathway." (PMID 34056009, 2021). "It will be of significance to further test the effects of lnc-ZNF281 in the treatment of human glioma." (PMID 34056009, 2021). "lnc-ZNF281 overexpression inhibited the proliferative and migrative abilities of glioma cells, while lnc-ZNF281 knockdown obtained the opposite findings." (PMID 34056009, 2021). "According to previous findings, the specific correlation between lnc-ZNF281 and glioma cells needs further exploration." (PMID 34056009, 2021). "The wound-healing assay and transwell assay results showed that overexpression of lnc-ZNF281 repressed the migrative abilities of glioma cells." (PMID 34056009, 2021). "The role of lnc-ZNF281 in regulating glioma and the potential molecular mechanism might provide a novel direction in the study of glioma occurrence and development." (PMID 34056009, 2021). "We wonder that whether lnc-ZNF281 suppressed the progression of glioma by AKT/GSK-3β/β-catenin pathway." (PMID 34056009, 2021). "Besides, lnc-ZNF281 suppressed glioma stem-like U251s cells growth and invasion by regulating the NF-κB signaling pathway." (PMID 34056009, 2021). "Consequently, these results above demonstrated that dysregulation of lnc-ZNF281 does regulate the biological process of glioma cells, which is worthy of further study." (PMID 34056009, 2021). "Then, a series of experiments were performed to investigate whether lnc-ZNF281 could regulate the progression of glioma cells." (PMID 34056009, 2021). "Results showed that lnc-ZNF281 had a low expression in glioma tissues." (PMID 34056009, 2021). "Taken together, lnc-ZNF281 inhibits glioma cell proliferation and migration via AKT/GSK-3β/β-catenin pathway and may serve as a potential target for glioma treatment." (PMID 34056009, 2021). "Besides, overexpression of lnc-ZNF281 in glioma cells inactivated the AKT/GSK-3β/β-catenin signaling pathway." (PMID 34056009, 2021). "Our study confirmed the downregulation of lnc-ZNF281 in glioma tissues." (PMID 34056009, 2021). "However, in glioma and non-small cell lung cancer, ZNF-281 has an opposite effect on carcinogenesis." (PMID 34071380, 2021). "In glioma and NSCLC, ZNF-281’s down-regulation is associated with carcinogenesis, indicating that ZNF-281 might also have cancer-suppressing properties." (PMID 34071380, 2021). "We performed qRT-PCR to detect the expression levels of lnc-ZNF281 in glioma tissues." (PMID 34056009, 2021). "Furthermore, β-catenin activation reversed the suppressive effects of lnc-ZNF281 on glioma cells." (PMID 34056009, 2021). "Thus, we performed this research to elucidate the effects and mechanisms of lnc-ZNF281 on glioma." (PMID 34056009, 2021). "Moreover, we revealed that lnc-ZNF281 might inhibit proliferation and migration in glioma via AKT/GSK-3β/β-catenin signaling pathway." (PMID 34056009, 2021).
glioma (continued). "Therefore, lnc-ZNF281 might become a novel direction for the research of biological progression of glioma, and it may be an effective target for glioma patients." (PMID 34056009, 2021). "The effects of lnc-ZNF281 on the proliferative and migrative abilities of T98G and HS683 glioma cells were examined by cell proliferation assay, colony formation assay, wound-healing assay, and transwell assay." (PMID 34056009, 2021). "For exploring the role of lnc-ZNF281 in glioma, we transfected T98G and HS683 cells with lentiviral vectors and siRNAs to structure stably transfected glioma cell lines, which was confirmed by qRT-PCR." (PMID 34056009, 2021). "The fact that, in glioma and NSCLC (contrary to the majority of cancers), ZNF-281 is down-regulated raises a question concerning whether ZNF-281 always has oncogenic properties." (PMID 34071380, 2021). "However, there are no reports that revealed the relationship between lnc-ZNF281 expression and the progression of glioma up to date." (PMID 34056009, 2021). "However, study on glioma cells has shown that lnc-RNA-ZNF281 (found in the ZNF-281 gene) might have a completely opposite effect on cancer progression and might inhibit glioma cell proliferation, migration and invasion, thus highlighting ZNF-281′s therapeutic value." (PMID 34071380, 2021).
neuroblastoma (4 papers, 2020 to 2023). Neuroblastoma (NB) is the most common solid, extracranial childhood tumor. "In addition, ZNF281 has been found to be a diagnostic marker for oral squamous cell carcinoma and a prognostic marker for neuroblastoma." (PMID 37939252, 2023). "ZNF281 inhibits the differentiation of neurons, and higher expression was proven related to a worse prognosis in neuroblastoma." (PMID 36685971, 2022).
colon adenocarcinoma (3 papers, 2020 to 2024). "Kaplan–Meier survival curves of sarcoma (left), colon adenocarcinoma (left), melanoma (left) and lung adenocarcinoma (left) patients demonstrated that high expression of ZNF281 significantly correlates with poor prognosis only in patients treated with genotoxic agents." (PMID 31570788, 2020). "ZNF281 highly expressed in BRCA (Breast invasive carcinoma), COAD (Colon adenocarcinoma), CHOL (Cholangiocarcinoma), ESCA (Esophageal carcinoma), HNSC (head and neck squamous cell carcinoma), LUAD (lung adenocarcinoma) and STAD (Stomach adenocarcinoma)." (PMID 38880820, 2024).
gastric cancer (3 papers, 2021 to 2024). A primary or metastatic malignant neoplasm involving the stomach. "So ZNF281 is associated with DNA damage and Wnt/β-catenin pathway and may affect chemotherapy sensitivity in gastric cancer." (PMID 38880820, 2024). "For instance, lnc-ZNF281 decreased miRNA-124 level to promote the migration and invasion of gastric cancer cells." (PMID 34056009, 2021). "The pathways with higher enrichment counts were not relevant to the core argument of the present study, but this may indicate that ZNF281 has other biological functions in gastric cancer." (PMID 38880820, 2024). "lnc-ZNF281 also promoted gastric cancer initiation and progression by targeting miR-124." (PMID 34056009, 2021).
hepatocellular carcinoma (3 papers, 2021 to 2025). A malignant tumor that arises from hepatocytes. "In hepatocellular carcinoma ZNF281 promotes tumor progression by suppressing mitochondrial biogenesis and function via repression of key mitochondrial TFs like NRF1 and PGC-1α." (PMID 41155227, 2025). "In this study, ZNF281 knockdown increased the expression of mitochondrial transcription factor A (TFAM) in hepatocellular carcinoma (HCC) cells, accompanied with increment of mitochondrial content, oxygen consumption rate (OCR) and levels of TCA cycle intermetabolites." (PMID 37880213, 2023). "However, upregulated lnc-ZNF281 was found in hepatocellular carcinoma tissues, and the interaction between lnc-ZNF281 and miR-539 played an oncogenic role in hepatocellular carcinoma progression." (PMID 34056009, 2021). "Correlation analyses between ZNF281 and the ETC subunits at the mRNA level were performed using data from the TCGA hepatocellular carcinoma database." (PMID 37880213, 2023).
sarcoma (3 papers, 2020 to 2024). A usually aggressive malignant neoplasm of the soft tissue or bone. "Accordingly, ZNF281/Zfp281 is down‐regulated during muscle differentiation, but its expression increases in human sarcomas." (PMID 31782884, 2020). "Pan-cancer survival analysis showed that ZNF281 expression was strongly associated with the prognosis of CESE (Cervical squamous cell), ESCA, KIRP (Kidney renal papillary cell carcinoma), LUAD, PAAD (Pancreatic adenocarcinoma), SARC (Sarcoma), STAD and UCEC (Uterine Corpus Endometrial Carcinoma)." (PMID 38880820, 2024). "Furthermore, a tendency to higher expression of ZNF281 was also detected in a panel of 46 sarcoma cell lines compared with nontransformed cell lines from soft tissues." (PMID 31782884, 2020).
soft tissue sarcoma (3 papers, 2020 to 2022). A malignant neoplasm arising from muscle tissue, adipose tissue, blood vessels, fibrous tissue, or other supportive tissues excluding the bones. "On the contrary, ZNF281 expression is associated with a worse prognosis in human soft tissue sarcomas." (PMID 36713370, 2022). "We extended our analysis to other human soft tissue sarcomas, in which the expression of ZNF281 is associated with a worse prognosis." (PMID 31782884, 2020). "The effect of ZNF281/Zfp281 in maintaining an undifferentiated phenotype is exploited in soft tissue sarcomas where the expression of this gene is elevated compared with normal counterparts and it is associated with a worse prognosis." (PMID 31782884, 2020). "Altogether, TMA and bioinformatic analyses suggest that the expression of ZNF281 is elevated in a wide range of soft tissue sarcomas." (PMID 31782884, 2020). "The elevated expression of ZNF281/Zfp281 in soft tissue sarcomas warrants further analysis for its possible exploitation as a prognostic marker in this class of tumors." (PMID 31782884, 2020). "Our analysis also reveals that elevated expression of ZNF281 compared to normal counterparts is a feature of several other soft tissue sarcomas." (PMID 31782884, 2020). "The elevated expression of ZNF281 in a vast range of soft tissue sarcomas warrants further investigation of the prognostic potential of this gene within this class of deadly tumors." (PMID 31782884, 2020). "Furthermore, they validated the higher expression of ZNF281 in certain types of soft-tissue sarcoma, such as rhabdomyosarcoma and leiomyosarcoma tumors." (PMID 36685971, 2022).
inflammatory bowel disease (2 papers, 2018 to 2022). A spectrum of small and large bowel inflammatory diseases of unknown etiology. "ZNF281 has also been shown to be significantly increased in the inflamed colon of patients with inflammatory bowel disease (IBD), and preliminary data have suggested its potential implication in gut fibrogenesis; however, the results are still limited and not exhaustive." (PMID 36142169, 2022).